TLR4 (toll like receptor 4)
Diseases named in the same sentence as TLR4 in open-access papers (continued):
Sharing a sentence is not in itself a finding about the gene and the disease.
Cerebral ischemia (continued). "Interestingly, one recent study investigated whether cerebral ischemia induced by MCAO for 2 hours differed in mice that lack functional TLR3 or TLR4 signaling pathways." (PMID 21982558, 2011). "In models of cerebral ischemia–reperfusion, KLK1 exhibits neuroprotective properties by upregulating the Nrf2 pathway and downregulating the TLR4/NF‐κB pathway." (PMID 41322027, 2025). "Treadmill exercise reduces TLR4 overexpression in cerebral ischemia, thereby lowering IL-6 secretion through the HMGB1/TLR4-mediated mechanism." (PMID 40843259, 2025). "TLR4 and C5AR1 promote apoptosis and inflammation by activating the cAMP/PKA/I- κB/NF- κB signaling pathway during brain ischemia-reperfusion." (PMID 38650649, 2024). "Since LPS is a canonical ligand that activates TLR4, we investigated the spatial distribution of HMGB1, an endogenous ligand of TLR4 released by damaged cells, after cerebral ischemia." (PMID 38082331, 2023). "Sal B significantly attenuated the protein expression of TLR4, p‐p38MAPK, p‐JNK, and IL‐1β compared with the tMCAO group at 24 and 72 h after cerebral ischemia (p < .05 for all)." (PMID 37904689, 2023). "The results of our study revealed that after cerebral ischemia, there is a significant increase in NDS, cerebral edema, and infarct volume, and TLR4, p‐p38MAPK, p‐JNK, and IL‐1β expression were all upregulated in the initial phase after tMCAO." (PMID 37904689, 2023). "To investigate the major signaling pathway during cerebral ischemia, we conducted KEGG pathway enrichment analysis, which revealed that the genes were mainly enriched in the TLR4/NF‐κB signaling pathway." (PMID 35263513, 2022). "Generally, JNK pathways are activated by TLR4/MyD88/TRAF6-, TLR4/T3JAM-, and ASK1-mediated signaling stimuli during cerebral ischemia." (PMID 34419138, 2021). "Human PRDX5 has been shown to enhance brain ischemia-reperfusion injury through activation of TLR2- and TLR4-mediated inflammation." (PMID 34943005, 2021). "In particular, Toll-like receptor 4 (TLR4) and TLR2 are considered to mediate the inflammatory response involved in the pathophysiological processes of cerebral ischemia-induced injury." (PMID 31440137, 2019). "We provide novel evidence that UA reduces inflammatory cytokine production to protect the brain from cerebral ischemia and reperfusion injury possibly through the HMGB1/TLR4/NFκB signaling pathway." (PMID 29867706, 2018). "In conclusion, UA attenuated inflammatory cytokine production to protect the brain against cerebral ischemia and reperfusion injury in a rat model possibly through HMGB1/TLR4/NFκB signaling pathway activation." (PMID 29867706, 2018). "Furthermore, TLR4, which is widely expressed on the plasma membranes of neural cells, has been demonstrated to play an important role in initiating the cerebral inflammation related to cerebral ischemia-reperfusion injury and intracerebral hemorrhage in TLR4-/- mice." (PMID 24669820, 2014). "Cerebral ischemia increases the central expression of both TLR2 and TLR4 that play opposite roles in the modulation of ischemic brain injury." (PMID 23251498, 2012). "Additionally, TLR2 and TLR4 act as independent mutants to increase vascular permeability after AIS, aggravating inflammatory injury after cerebral ischemia." (PMID 40520774, 2025). "Thus, TLR4/MyD88/NF-κB signaling pathway exerts vital importance on regulating NLRP3 activation, neuronal pyroptosis and microglia activation after cerebral ischemia." (PMID 38273974, 2023). "Our subsequent results also confirmed that iTBS could down-regulate the high level of TLR4, NLRP3, and phosphorylation of NFκB induced by cerebral ischemia." (PMID 35690810, 2022). "As an ingredient of Carthami flos, luteolin could downregulate the expression of TLR4, TLR5, NF-κ B, and P-P38MAPK, upregulate the expression of p-ERK, and protect cerebral ischemia in rats." (PMID 33727944, 2021).
Cerebral ischemia (continued). "Moreover, in cerebral ischemia, the TLR-4 pathway is regulated by NF-kB, and a reduction in TLR-4 expression decreases inflammation in ischemic stroke." (PMID 32997222, 2020). "For example, in a mouse model of focal cerebral ischemia-reperfusion injury, NLRP3 inflammasome inactivation was mediated by inhibition of the TLR4/NF-κB signaling pathway, which resulted in HMGB1 downregulation, consequently alleviating brain damage in ischemic stroke." (PMID 33384585, 2020). "We investigated whether UA reduced inflammatory cytokine production to protect the brain from cerebral ischemia and reperfusion injury possibly though the HMGB1/TLR4/NFκB signaling pathway." (PMID 29867706, 2018). "In this study, we found vinpocetine exerts a protective role on a cerebral ischemia and reperfusion model by inhibiting TLR4/MyD88/NF-κB signaling, but not the TLR4/TRIF/NF-κB signaling pathway, in vitro and in vivo." (PMID 29113305, 2017). "The results of the present study indicated that paeonol pretreatment can reduce cerebral infarction volume; neurological deficits; TLR2-, TLR4-, Iba1-, NF-κB-, and IL-1β-immunoreactive cell numbers; and TUNEL-positive cells in cerebral ischemia-reperfusion injured rats." (PMID 28101118, 2016). "Mice lacking TLR4 receiving pre-conditioning prior to permanent cerebral ischemia are not protected and show reduced NF-κB activation and lower expression levels of TNF-α compared to wild-type animals." (PMID 25239168, 2014). "Recently, TLR4 and TLR9-induced tolerance to cerebral ischemia has been well studied." (PMID 21982558, 2011). "In adult studies, TLR-4 has been found to be up-regulated after cerebral ischemia reperfusion and mice lacking TLR-2 or TLR-4 are less susceptible to hypoxic/ischemic brain damage." (PMID 21569241, 2011). "The long-term inflammatory response of muscle after cerebral ischemia serves as a key therapeutic target, and HIIT may regulate macrophage polarization via inhibiting the TLR4/MyD88/NFκB signaling pathway, thereby reducing the cytotoxicity and proinflammatory properties of macrophages." (PMID 34845407, 2021). "TLR4 is expressed primarily in microglia and astrocyte in the central nervous system and can be activated by DAMPs (such as HMGB1) to induce downstream signals that lead to cytokine production and thus initiation of an inflammatory response after cerebral ischemia and reperfusion injury." (PMID 29867706, 2018). "Therefore, the roles of TLR4 in ICH and cerebral ischemia may be different." (PMID 23414417, 2013).
depression (163 papers, 2011 to 2026). "In contrast, males tend to produce more proinflammatory cytokines through Toll-like receptor 4 activation by pathogens, rendering them more susceptible to chronic, inflammation-mediated depression and cognitive decline." (PMID 41417415, 2025). "Growing evidence suggests that TLRs are associated with the pathophysiology of major depressive disorder, among which multiple linear regression analysis revealed that TLR4 was an independent risk factor relating to the severity of major depression." (PMID 39749341, 2024). "The TLR4 signaling pathway has been identified as a key player in the inflammatory processes associated with depression (L. Wang and Chen 2017)." (PMID 39538967, 2024). "Further research is needed to explore the long‐term effects and safety profile of Fructus arctii in diverse populations, as well as to elucidate the precise mechanisms underlying the interaction between let‐7e and TLR4 in depression." (PMID 39538967, 2024). "Stress is an indirect cause of depression, which induces depression-like behaviors through the HMGB1/TLR4/NF-κB signaling pathway in the hippocampus." (PMID 36388178, 2022). "Previous studies demonstrated that depression-like behaviors caused by stress were dependent on HMGB1/TLR4/NF-κB and TNF-α/TNFR1/NF-κB signalling pathways in CUMS-exposed mice." (PMID 35386281, 2022). "How does the TLR4/NLRP3 inflammasome signaling pathway induce the inflammation-associated immune response in depression?" (PMID 33505499, 2021). "Higher depression scores in young Scandinavian adults was associated with decreased methylation of TLR4 in blood." (PMID 34226490, 2021). "Puerarin treatment alleviated HFD/CUMS-induced depression-like behavior by inhibiting TLR4-associated inflammatory responses." (PMID 34975477, 2021). "TLR4 is highly expressed in brain microglia, and excessive inflammation resulting from the activation of this pathway in the brain has been implicated in depressive disorders and neurodegenerative pathologies." (PMID 32328132, 2020). "Although microRNA-associated pathways were analyzed in patients with depression, to our knowledge, limited studies assessed the effects of intracellular microRNA on TLR4 signaling related to MDD." (PMID 31252530, 2019). "This study aimed to assess the association between the severity of depression and the intracellular microRNAs that regulate TLR4 signaling in both peripheral blood mononuclear cells (PBMCs) and monocytes from MDD patients." (PMID 31252530, 2019). "The calcium-binding protein p11 is linked with the transport of neurotransmitters and depression and data from cell lines confirm that it is regulated by immunological parameters like TLR-4." (PMID 30180869, 2018). "Multiple linear regression analysis revealed that TLR4 is an independent risk factor relating to severity of major depression." (PMID 27478433, 2016). "Within the brain, TLR4 is highly expressed in brain microglia, and excessive inflammation resulting from activation of this pathway in the brain has been implicated in depressive disorders and neurodegenerative pathologies." (PMID 23555964, 2013). "The Lbp-Tlr4-Netrin-1 axis was highly upregulated in depressed subchondral bone, and its inhibition alleviated both pain-like behaviors and excessive bone resorption while mitigating depression-related weight loss." (PMID 41711199, 2026). "Modern research has found that QFY can inhibit the TLR4/NF-κB pathway, thereby reducing neuroinflammation, the activation of the TLR4/NF-κB pathway is associated with anxiety and depression-like symptoms, therefore, it is inferred that QFY has therapeutic potential for depressive symptoms." (PMID 40438332, 2025). "Studies have shown that activation of the TLR4 complex might underlie the pathophysiology of stress-evoked depression." (PMID 37917302, 2024).
depression (continued). "Recent findings have revealed that the TLR4 single gene polymorphisms were associated with suicide and anxiety scores in depression patients, while methylation levels of TLR4-associated CpGs were identified to be associated with the severity of depressive symptoms." (PMID 37917302, 2024). "Administration of the inflammasome inhibitors VX-765, E2 and ERβ agonists to ovariectomized mice blocked these signaling pathways by inhibiting P2X7R, TLR2 and TLR4 expression, thereby reversing depression and anxiety-like behaviors caused by estrogen deficiency." (PMID 38898454, 2024). "TLR4 is associated with a wide array of systemic and central nervous system (CNS) disease-like states, such as sepsis, rheumatoid arthritis, chronic obstructive pulmonary disease, depression, schizophrenia, and bipolar disorder." (PMID 39595617, 2024). "In addition, in human studies, the methylation status of a TLR4 promoter-associated CpG and the level of TLR4 gene expression correlate with symptoms of depression." (PMID 37296629, 2023). "Intervention targeting the HMGB1/TLR4/NF-κB pathway could alleviate neuroinflammation and improve cognitive impairment in models of depression, cognitive impairment caused by high-fat and high-sugar diets, and traumatic brain injury." (PMID 36552192, 2022). "Increased TLR4 signaling and mRNA TLR4 expression are both associated with depression." (PMID 35330475, 2022). "Most importantly, TLR4 was an independent risk factor associated with depression severity." (PMID 36358493, 2022). "Most important is that TLR4 is an independent risk factor related to the severity of depression." (PMID 34975477, 2021). "Studies have shown that chronic restraint stress induces depression-like behavior in mice, which is associated with microglial activation and upregulation of TLR4/p38 and P2X7 receptors in the hippocampus, and this neurobehavioral and biochemical abnormality is normalized by ketamine treatment." (PMID 34079622, 2021). "Additionally, TDZD-8 attenuates an increased activation of NF-κB upon TLR4 stimulation, which indicates that GSK3 mediates a TLR4-related pro-inflammatory reaction associated with depression-like behavior." (PMID 32188010, 2020). "Since our previous study has demonstrated that TNF‐α is a common risk factor in depressive disorders induced by both stress and inflammation, we further investigated whether antidepressant effect of TLR4 is via inhibition of TNF‐α production." (PMID 31945269, 2020). "Since this receptor can be activated by saturated fatty acids, which are associated with higher risk of developing T2D, a pathway involving TLR4, TNFα, and insulin resistance could be a mechanistic link between T2D and depression yet to be explored." (PMID 30837902, 2019). "Therefore, there is a plausible linkage of TLR4 to the production of pro-inflammatory cytokines, which, in turn, contribute to vascular dysfunction associated with depression and DM." (PMID 25826421, 2015). "In addition to acute sickness and depression, TLR4 activation in microglia has also been linked to neurodegeneration." (PMID 23555964, 2013). "Thus, the decreased miR-135a-5p levels in depressive patients may concurrently decrease its repressive role on TLR4, leading to stronger inflammatory effects in corresponding tissues, such as the brain, and enhancing susceptibility to depression." (PMID 40598020, 2025). "Finally, it is important to acknowledge that the TLR4 deletion in this study had broader effects on brain regions implicated in depression, including the hippocampus, amygdala, nucleus accumbens, and others, rather than being specific to the prefrontal cortex (PFC)." (PMID 37838079, 2024). "LPS administration induced depression-like behavior, which may be associated with TLR4 activation." (PMID 37173696, 2023). "Activation of the TLR4 complex might underlie the pathophysiology of stress-evoked depression." (PMID 31068207, 2019).
depression (continued). "These cytokines influence depression-related pathophysiology by activating innate immune signaling pathways, including TLR4, NF-κB, MAPK, and the NLRP3 inflammasome, while also reshaping tryptophan-kynurenine metabolism through IDO1 and TDO2." (PMID 42212166, 2026). "TLR4 and RB1 were identified as core genes, showing elevated expression and strong diagnostic potential in depression." (PMID 42253512, 2026). "LLE improved CRS-induced anxiety- and depression-like behaviors, reduced microglial activation in the hippocampus, and suppressed TLR4/MyD88/NF-κB signaling and downstream cytokine release (TNF-α, IL-6, IL-1β)." (PMID 42255668, 2026). "In LPS-induced models of depression, an endotoxin challenge activates the immune system through toll-like receptor 4 (TLR4)." (PMID 40487411, 2025). "This and a synergistic mechanism via increased expression and activation of the TLR4 is involved in the activation of the innate immune system in some forms of depression." (PMID 41155634, 2025). "Punicalin, a polyphenol found in pomegranate fruits, inhibits the TLR4/NF-κB signaling pathway and alleviates LPS-induced pathological behaviors, including depression." (PMID 40936908, 2025). "Of interest in the context of atypical depression is the observation that TLR4 knockout mice have less sleep need and a smaller increase in sleep rebound after sleep deprivation." (PMID 41155634, 2025). "Raspberries, globally known for their pleasant flavor, contain raspberry ketone, a phenolic compound that reduces LPS-induced depression-like behaviors in mice by inhibiting the TLR4/NF-κB pathway and modulating the MGB axis." (PMID 40936908, 2025). "LPS is used to induce acute inflammatory stress to generate mouse models of depression, in which LPS activates microglia via the TLR4/NF-κB pathway." (PMID 41208869, 2025). "In corticosterone-induced mice, persistent activation of the TLR4/NF-κB p65, JAK2-STAT3, and AKT-GSK3β pathways was detected, aligning with neuroinflammatory cascades associated with depression." (PMID 41190144, 2025). "An increased brain expression of TLR4 has been observed in a broad range of neuropsychiatric disturbances, including major depression." (PMID 41155634, 2025). "Modulating the GM with XCHT downregulated the TLR4/MyD88/NF-κB pathway, inhibiting tumor growth and improving systemic inflammation in a depression-comorbidity model." (PMID 41561086, 2025). "Our findings reveal that DSS mitigates hippocampal neuroinflammation and enhances hippocampal neurogenesis in depression model mice via modulation of the TLR4/NF-κB p65, JAK2/STAT3 and AKT-GSK3β signaling pathways." (PMID 41190144, 2025). "In a study using a CUMS model of depression, the TLR4/MyD88/NF-κB and HIF-1α-VEGF signaling pathways in the hippocampus underwent significant changes, contributing to neuroinflammation and depressive behaviors." (PMID 40149760, 2025). "In the inflammatory response accompanying the onset of depression, TLR4, indoleamine 2,3-dioxygenase (IDO) and NLRP3 play important roles, with activation of NLRP3 inflammasome being more critical." (PMID 41179813, 2025). "In summary, our findings demonstrate that Fructus arctii mitigates depressive disorder via the let‐7e‐mediated TLR4/MyD88 signaling pathway, suggesting its potential as a therapeutic agent for depression." (PMID 39538967, 2024). "Acupuncture prevented CUMS-induced depression-like behaviors by reversing the hyper-activation of the HMGB1/TLR4 signaling pathway and by downregulating IL-1β, TNF-α, and IL-6 in the amygdala (AMY) and blood of rats." (PMID 38791125, 2024). "Clinical studies have found that patients with IBS and depression have higher levels of TLR4 expression and IL-6, accompanied by a decrease in IL-10, which indicates that TLR participates in the inflammation reaction in IBS and depression." (PMID 39749341, 2024). "Here we showed that TMZ is an affluent nominee for depression management via targeting TLR4/NF-κB and Nrf2/HO-1 pathways." (PMID 39312021, 2024).